CD4 (CD4 molecule)
Diseases named in the same sentence as CD4 in open-access papers (continued):
Sharing a sentence is not in itself a finding about the gene and the disease.
cancer (continued). "Across 33 TCGA cancer types and six cancer subtypes, only LIHC showed a significantly positive correlation between YBX3 expression and the infiltration of all six immune cell types (neutrophils, macrophages, dendritic cells, CD8+ T cells, CD4+ T cells, and B cells)." (PMID 36059530, 2022). "The highly expressed cytokine CCL5 in CD8 + T Cells, NK Cells, NKT Cells, CD4 + T Memory Cells, Plasma Cells, and Langerhans Cells work together with SDC1 and SDC4 in Cancer Cells to affect the occurrence, development, and mediation of cancer survival of cancer cells." (PMID 36401283, 2022). "In the TME, PD-L1 is also widely expressed on immune cells (such as CD4(+) T cells, CD8(+) T cells, Treg cells, B cells, Langerhans cells, and monocytes) and non-immune cells (such as vascular endothelial cells, and various mesenchymal cells) in addition to cancer cells." (PMID 36626519, 2022). "However, the risk of HIV-associated cancers remains higher in adults with HIV than in HIV negative adults, even after prolonged use of ART, suppression of HIV viral load, and restoration of CD4 lymphocyte counts." (PMID 33803641, 2021). "In comparison to CD4+ T cells restimulated polyclonally in the absence of cancer cells, we found a profoundly greater increase in the production of PD-1 and PD-L1 proteins in CD4+ T cells restimulated in the presence of cancer cells." (PMID 34439305, 2021). "Although tumoral exosome‐PD‐L1 has been reported to be deleterious for cancer patients, our findings indicate that WJMSC sEV‐PD‐L1 might indeed be beneficial for treating aGvHD patients through targeting CD4+ T cells." (PMID 33598108, 2021). "Also, CD4+ infiltration was not altered in a breast cancer mice model when exercise started two weeks before cancer cells’ injection." (PMID 33808154, 2021). "While IA1 and IA2 stimulated similar proliferative effects (12.2 ± 1.2 and 10.7 ± 0.5%, respectively), their impacts on CD4/CD8 differentiation were vastly different and, as observed in our previous study, IA1 and IA2 exhibited distinct biological activities and anti-cancer mechanisms." (PMID 34677693, 2021). "Besides, compared to non-cancer patients, the COVID-19 patients with cancer have significantly higher circulatory levels of proinflammatory cytokines and lower concentrations and viability of CD4 T cells and CD8 T cells." (PMID 34277453, 2021). "Interestingly, the exchange of PRC2 subunit EZH2 and SWI/SNF ATPase subunits BRM and BRG1 was observed in CD4+ T cells restimulated and growing with cancer cells as compared to control without cancer cells." (PMID 34439305, 2021). "On the other hand, the overexpression of the CD274 gene encoding PD-L1 was found in deep transcriptome analysis, while the metabolism- and angiogenesis-related genes were upregulated in T15M samples compared to control T15 and T12 CD4+ cells, which were not exposed to cancer cells." (PMID 34439305, 2021). "We could clearly detect all major cell lineages in the cancer patient PBMCs, which matched the ones from healthy donors, including monocytes, neutrophils, B cells, NK cells, as well as CD4+, CD8+ or double negative T cells." (PMID 33668625, 2021). "In addition, RNA vaccine could be another effective immunotherapy, which drives immunity by the induction of strong CD4+ and CD8+ T-cell immunity against the vaccine antigens to kill cancer cells." (PMID 34589427, 2021). "In addition, the prognostic value of CD4+ T and FOXP3+ T cells requires further investigation due to protumoral and antitumoral functions that have been postulated for FOXP3 TILs’ (Tregs’) expression in different cancers." (PMID 34201050, 2021). "To further validate our LDH release assay data, and to determine if the cytotoxicity resulted from target cell (cancer cell) death and not effector cell (CD4+T cell) death, we labeled the cancer cells with PHK26 and performed flow cytometry-based cytotoxicity studies." (PMID 33918403, 2021).
cancer (continued). "Fractions of (i) individual non-malignant cell-types for which a GEP is provided (ii) all the other non-characterized (cancer) cell types grouped together.The package provides reference GEPs for B, CD4 T, CD8 T, NK, CAFs, Endothelial, Macrophages, Monocytes, Neutrophils." (PMID 35069581, 2021). "Furthermore, analysis using TIMER database and gene expression studies indicates that high levels of DVL-1 are inversely correlated with target genes including infiltration of CD8+ and CD4+ T cells, highlighting a potential connection of DVL-1 in cancer immunomodulation." (PMID 34659647, 2021). "However, a generalized recommendation of a high salt diet to induce anti-cancer inflammatory CD4+T cell responses in cancer patients would be a non-viable option." (PMID 33918403, 2021). "We quantified the frequencies of CD4+CD25+FOXP3+ Tregs in all groups and found a significant reduction in Tregs in the C + I vaccine group compared with PBS in both TDLNs and the spleen, reversing the immune-suppressive microenvironment in mice injected with cancer cells." (PMID 33961792, 2021). "During the “elimination” phase, the natural killer (NK) cells, CD4+Th1, CD8+CTL (cytotoxic T lymphocyte), and cytokines including tumor necrosis factor-α (TNF-α), interferon-α, interferon-β, interferon-γ and interleukin-12(IL-12) are the primary factors to recognize and eliminate cancer cells." (PMID 35127500, 2021). "However many other conventional immune checkpoints such as TIGIT, TNFRSF4 (OX40 receptor/CD134), TNFRSF9 (4-1BB/CD137), and TNFRSF18 (GITR) are not universally overexpressed in cytotoxic CD4+ T cells from cancer patients." (PMID 34910940, 2021). "Next, we analyzed the enrichment score of all TIME elements and RBCK1 in pan-cancers and found that the expression of RBCK1 was significantly correlated with increased numbers of immune cells, including B cells, Th2 cells, M1 macrophages, and the decreased numbers of CD4+ T cells and Treg cells." (PMID 34795663, 2021). "Importantly MSI-H tumors could show favorable prognosis/improved response to cancer immunotherapy due to elevated levels of CD8+ TILs and elevated levels of IC-expressing CD4+ TILs compared to MSS tumors." (PMID 33477864, 2021). "In addition, SLC1A5 mRNA correlated significantly with the extent of infiltration of B cells in 14 cancer types, CD4+ cells in 15 cancer types, CD8+ cells in 12 cancer types, DC in 20 cancer types, macrophages in 17 cancer types, and neutrophils in 17 cancer types." (PMID 34367941, 2021). "However, the modality of CD4 T cell plasticity in the context of cancer is not yet totally understood." (PMID 32121394, 2020). "It has been demonstrated that TCR signalling could abrogate the anti‐cancer effect of CD8+ CAR T cells but not CD4+ T cells through reduced expansion, increased apoptosis and exhaustion in a CD19+ ALL murine model." (PMID 32704371, 2020). "CD4 gene expression was higher in cancer samples but statistical significance was not reached." (PMID 32383556, 2020). "Furthermore, we used flow cytometry to isolate the cancer cells and T cells in 12 GGN-ADC samples and in an equal number of SADC samples, including CD4+ T and CD8+ T cells, and validated the expression of key molecules by quantitative real-time polymerase chain reaction analyses." (PMID 33083004, 2020). "Notably, CD4+ T cells can exert cytotoxicity and as such can direct cancer cell rejection in the absence of CTLs." (PMID 33353155, 2020). "Cancer cells infected with oncogenic HPV genotypes develop a series of immune evasion mechanisms; thus, several strategies have been investigated to tackle them by enhancing CD4+ and CD8+ T cell responses such as gene-based, protein-based, peptide-based and dendritic-cell-based vaccines." (PMID 33375467, 2020).
cancer (continued). "Among anti-cancer immune cells, M1 macrophages, activated NK cells, T follicular helper cells, memory B cells, activated memory CD4+ T cells, and γδT cells were the lowest in the non-inflamed phenotype and highest in hot T-cell infiltrated phenotype in both the TCGA BC cohort and METABRIC cohort." (PMID 33396390, 2020). "Blockade of the PD-L1/PD-1 axis in a helpless setting increases the magnitude of the antigen-specific CD8+ T cell response, but in contrast to CD4+ T cell help, it did not rescue the formation of the effector population that conferred protection against chronic infection and cancer." (PMID 33123174, 2020). "The ratio of CD4+ T cells to CD8+ T cells are an important factor in determining immunity states and levels, and plays a central role in the induction of efficient immune responses against different diseases such as human immunodeficiency virus (HIV) and cancer." (PMID 32046726, 2020). "Since PLAs have not been assessed in cancer patients, we assessed several leukocyte populations for interaction with platelets: total leukocytes, neutrophils, monocytes, natural killer cells, T cells (CD4+ and CD8+), and B cells." (PMID 32776968, 2020). "Notably, multifunctional CD4+ and CD8+ T cells capable of producing multiple Th1 cytokines (IFN-γ, TNF-α, IL-2) and expressing the degranulation marker (CD107a) play a critical role in cancer protection." (PMID 33105813, 2020). "In this study, we investigated the role of Yap in primary CD4+ and CD8+ T-cell responses—namely, activation, proliferation, and differentiation into effector T-cell subsets—and how Yap might affect T-cell responses in cancer." (PMID 31929526, 2020). "Interestingly, murine models of cancer have revealed that CD4+ T cells can also infiltrate tumors independent of antigen specificity." (PMID 32859954, 2020). "The expanded T cells were primarily CD8+ T cells with no or very low levels of CD4+ T cells in cultures of expanded NK cells from both healthy individuals and cancer patients, and the relative CD4+/CD8+ T cell ratios remained similar between cancer patients and healthy individuals." (PMID 33230147, 2020). "Low activity of Yap-regulated CD4+ and CD8+ gene expression signatures correlated with immune infiltration in 19 TCGA cancer types—and strongly correlated with survival in 11 TCGA cancer types—highlighting that Yap activity in T cells has broad potential as a target for cancer therapy." (PMID 31929526, 2020). "In addition, LCN2 expression was notably correlated with the infiltration levels of CD4+T cells in 13 cancer types, B cells in 12 cancer types, CD8+T cells in seven cancer types, macrophages in 10 cancer types, neutrophils in 12 cancer types, and dendritic cells in 20 cancer types." (PMID 33425761, 2020). "In fact, studies have described a negative relationship between peripheral CD4+FoxP3+ regulatory T cell levels and clinical response to adoptive immunotherapy of human cancer, suggesting that Tregs mediate the inhibitory effects of adoptive immunotherapy on human tumors." (PMID 32964058, 2020). "Finally, a variety of novel high-throughput immunological screening methods, with enhanced capacity to interrogate large numbers of candidate neoepitopes, are used to screen cancer-derived CD8+ and CD4+ T-cell populations of interest for neoantigen recognition." (PMID 31293573, 2019). "The role of PFRs during CD4+ T-cell recognition of cancer epitopes has not been well-defined and may represent an opportunity to design optimized peptides for vaccine or other therapeutic approaches." (PMID 31619516, 2019). "The higher mortality amongst adults above 45 years is potentially attributed to other old-age related illness, including non-communicable diseases (heart related or cancer), low CD4 counts or drug resistance which are not routinely collected for the TIBU database." (PMID 31295277, 2019).
cancer (continued). "Then, we thought that G2 patients could be refractory to anti‐PD‐1 immunotherapy by not having systemic cancer‐specific CD4 T cells." (PMID 31273938, 2019). "The relationship between host immune status and cancer cells is incompletely understood, and there has been a significant recent interest in the interaction between cancer and the host’s immune status (e.g., CD4+ count, CD8+ count, CD4: CD8 ratio, and CD56+ fraction of peripheral lymphocytes)." (PMID 30991692, 2019). "Thus far, the development of cancer vaccines solely focusing on CD8+ T cell epitopes has not been particularly successful without considering CD4+ T cell help." (PMID 31379821, 2019). "Thus, independent of their function in providing help, CD4+ T cells can be generated that can directly target cancer cells for elimination." (PMID 31379821, 2019). "This process facilitates anti-cancer immunosurveillance, represented by the higher amount of infiltrating mature DCs and effector T cells in the case of NSCLC patients and increased numbers of circulating NK cells and IFN-γ producing CD4+ and CD8+ T cells in AML patients." (PMID 31041312, 2019). "Importantly, the percentage of both CD4+ (13.8 to 23.0%) and CD8+ T (9.7 to 17.8%) cells in the blood doubled after acGM-1.8 treatment, providing further evidence of the restoration of anti-cancer adaptive immunity." (PMID 31118418, 2019). "Melanoma was the first model to reveal CD4+ and CD8+ cellular specificity to cancer differentiation antigens gp100 and tyrosinase, suggesting the immunogenicity of the tumor and the ability of the patient’s own immune system to recognize and activate a specific immune response against cancer cells." (PMID 29534457, 2018). "However, since most cancer cells do not express MHC class II molecules the efficacy of CD4+ based immunotherapy in se is rather limited." (PMID 29770138, 2018). "It has been suggested that CAFs suppress T-cell infiltration into cancers, and also through secretion and activation of TGF-β, modulate multiple types of immune cells towards a more suppressive phenotype, including tolerization of CD4 T cells and promotion of a regulatory T cell phenotype." (PMID 29740440, 2018). "For example, in addition to theWHO recommendation that all HIV-infected people receive ART regardless of CD4 count,patients with cancer may need expedited ART referral to facilitate immunologicsupport during chemotherapy." (PMID 30241139, 2018). "Although CD4+ T cells with distinct CD26 expression profiles exhibit unique immunological properties in healthy donors, it is unclear whether these biological assets are similar in cancer patients." (PMID 29213079, 2017). "The impact of these mechanisms of immune evasion has been convincingly shown in cancer patients and may result in the formation of cancer cells that are no longer subject to surveillance by CD4 or CD8 T cells." (PMID 29312332, 2017). "Elevated levels of CD4+ T cells co-expressing CTLA-4 and PD-1 also support the dual blockade of these immunosuppressive pathways, which could be a more effective method for treating different cancers including breast." (PMID 28388539, 2017). "From the analysis of data on differential changes in the expression of CD95 and the level of apoptosis in CD4 and CD8 subsets of peripheral blood T cells available from published sources, it can be inferred that these changes exhibit different patterns depending on the type of cancer." (PMID 29075318, 2017). "The marked increase in CD4+FoxP3+ Treg levels in TT compared to NT and peripheral blood of CRC patients in our study was in accordance with previously published reports from other groups, where an expansion in Treg levels in TILs in various cancers including CRC was demonstrated." (PMID 28603527, 2017). "Furthermore, some authors claim that activated CD4+CD25+ Tregs may express granzyme and perforin and lead to the death of cancer cells via a perforin/granzyme dependent pathway." (PMID 29209232, 2017).
cancer (continued). "In cancer, this T-cell help may not be inducible by cancer antigens themselves as multiple immune tolerogenic mechanisms exist to dampen induction of CD4+ Th cells to these self-proteins." (PMID 27471642, 2016). "However, further studies are required to confirm the roles of CD4 and CD74 in cancers." (PMID 27323782, 2016). "In addition to their CD4+ T cell activating capacities, all three subsets can cross-present exogenous antigens for cognate restimulation of previously activated CD8+ T cells, making them promising candidates for DC-based vaccination strategies against cancer." (PMID 27057096, 2016). "In addition, Kaplan-Meier analyses further demonstrated that the 5-year OS and RFS probabilities were both above 80% in CD4+ T cells ≤16 (median expression levels in cancer tissue) cancer patients, whereas only about 50% of OS and RFS in CD4+ T cells > 16 patients." (PMID 25968569, 2015). "Thus, the activated antigen-specific CD4+ T cells interact with MDSCs loaded with specific antigens, converting these cells to non-specific suppressors in cancers." (PMID 26497849, 2015). "In addition, active evasion by cancer cells from attack and elimination by immune cells, mainly CD8+ cytotoxic T lymphocytes, CD4+ Type 1 helper T cells, and natural killer (NK) cells, highlights the dual role of an immune system that both antagonizes and promotes cancer development and progression." (PMID 25101079, 2014). "Hsp90 is also required for Type I and II interferon signaling, so that its inhibition may result in impaired responses to these important anti-cancer cytokines, and reduced expression of both Class I and Class II antigens needed for CD8+ and CD4+ T cell receptor specificity." (PMID 25503774, 2014). "In addition, an arabinoxylan isolated from rice bran increased CD4+ T cell function in human monocyte-derived dendritic cells, and increased T and B cell proliferation in both humans with and without cancer." (PMID 24755139, 2014). "The ability of this vaccine to work in the absence of CD4+ T “helper” cells may be translationally important in the context of cancer patients (e.g., HIV-infected and some after chemotherapy) who are frequently deficient in (Type-1) CD4+ Th function." (PMID 25941586, 2014). "Although Nrp1+ CD4+ T cells may co-express CD25 and exert regulatory function in some cancer-draining lymph nodes, in non-malignant lymph nodes and tonsils, Nrp1+ CD4+ T cells have a non-regulatory (CD25- FoxP3-) memory (CD45RA- CD45RO+) phenotype." (PMID 24386482, 2013). "The fact that leukocytes depleted of both CD4+/CD8+ and B cells from the cancer resistant donor mice could be transferred to inhibit S180 cancer cell growth in susceptible recipient mice support the vision of an efficient and adverse event free immunotherapy in future selected cancer types." (PMID 23555858, 2013). "Healthy women participating in regular exercise had significantly lower percentage of circulating CD4+/CD25+/FOXP3 Tregs, compared with women that were more sedentary.Thus, exercise training during cancer treatment may help reduce the immunosuppressive effects of Tregs." (PMID 24312199, 2013). "CD3 and CD4+ cells were lower in all treatment groups than in the control group, CD3 were significantly lower in the high ASMq dose and 2 g/kg ASMq groups than in the untreated cancer model (p <0.05), a pattern also reproduced for CD4 cells, though not significantly." (PMID 22978453, 2012). "Treatment with GL tended to increase mitogenic reactivity to phytohemagglutinin, counts of CD3, CD4, CD8 and CD56 lymphocytes, plasma concentrations of interleukin (IL)-2, IL-6 and interferon (IFN)-γ, and NK activity, whereas plasma concentrations of IL-1 and TNF-α were decreased in cancer patients." (PMID 19617199, 2011).